CAMK2D (calcium/calmodulin dependent protein kinase II delta)
Description:
Calcium/calmodulin-dependent protein kinase involved in the regulation of Ca(2+) homeostatis and excitation-contraction coupling (ECC) in heart by targeting ion channels, transporters and accessory proteins involved in Ca(2+) influx into the myocyte, Ca(2+) release from the sarcoplasmic reticulum (SR), SR Ca(2+) uptake and Na(+) and K(+) channel transport. Targets also transcription factors and signaling molecules to regulate heart function. In its activated form, is involved in the pathogenesis of dilated cardiomyopathy and heart failure. Contributes to cardiac decompensation and heart failure by regulating SR Ca(2+) release via direct phosphorylation of RYR2 Ca(2+) channel on 'Ser-2808'. In the nucleus, phosphorylates the MEF2 repressor HDAC4, promoting its nuclear export and binding to 14-3-3 protein, and expression of MEF2 and genes involved in the hypertrophic program. Is essential for left ventricular remodeling responses to myocardial infarction. In pathological myocardial remodeling acts downstream of the beta adrenergic receptor signaling cascade to regulate key proteins involved in ECC. Regulates Ca(2+) influx to myocytes by binding and phosphorylating the L-type Ca(2+) channel subunit beta-2 CACNB2. In addition to Ca(2+) channels, can target and regulate the cardiac sarcolemmal Na(+) channel Nav1.5/SCN5A and the K+ channel Kv4.3/KCND3, which contribute to arrhythmogenesis in heart failure. Phosphorylates phospholamban (PLN/PLB), an endogenous inhibitor of SERCA2A/ATP2A2, contributing to the enhancement of SR Ca(2+) uptake that may be important in frequency-dependent acceleration of relaxation (FDAR) and maintenance of contractile function during acidosis. May participate in the modulation of skeletal muscle function in response to exercise, by regulating SR Ca(2+) transport through phosphorylation of PLN/PLB and triadin, a ryanodine receptor-coupling factor. In response to interferon-gamma (IFN-gamma) stimulation, catalyzes phosphorylation of STAT1, stimulating the JAK-STAT signaling pathway (By similarity).
Synonyms: CAMKD
Tractability: Small molecule: a structure with a bound ligand is known; a high-quality ligand is known; it has a high-quality binding pocket; it belongs to a druggable protein family. Antibody: UniProt places it where antibodies can reach, with high confidence; its Gene Ontology location is reachable by antibodies, with medium confidence; the Human Protein Atlas places it where antibodies can reach. PROTAC: ubiquitination databases record sites on it; its protein half-life has been measured; a small molecule that binds it is known.
Target class: CAMK protein kinase CAMK2 family; Protein Kinase; Enzyme; CAMK protein kinase group; Kinase
Gene: Protein-coding gene on chromosome 4 (113,418,054 to 113,761,927, reverse strand). Ensembl gene ENSG00000145349.
Subcellular location: Cell membrane, sarcolemma; Sarcoplasmic reticulum membrane
Subcellular location (Human Protein Atlas): Plasma membrane; Primary cilium tip; Primary cilium transition zone; Principal piece; Calyx; Cell Junctions; Connecting piece; End piece; Perinuclear theca
Pathways (Reactome):
Disease: Dengue Virus-Host Interactions; Paradoxical activation of RAF signaling by kinase inactive BRAF; Signaling by BRAF and RAF1 fusions; Signaling by RAF1 mutants; Signaling by moderate kinase activity BRAF mutants; Signaling downstream of RAS mutants
Neuronal System: Assembly and cell surface presentation of NMDA receptors; Long-term potentiation; Negative regulation of NMDA receptor-mediated neuronal transmission; Ras activation upon Ca2+ influx through NMDA receptor; Trafficking of AMPA receptors; Unblocking of NMDA receptors, glutamate binding and activation
Signal Transduction: CaMK IV-mediated phosphorylation of CREB; RAF activation; RAF/MAP kinase cascade
Muscle contraction: Ion homeostasis; Phase 0 - rapid depolarisation
Cellular responses to stimuli: HSF1-dependent transactivation
Immune System: Interferon gamma signaling
Transport of small molecules: Ion transport by P-type ATPases
Gene Ontology:
Molecular function: calcium/calmodulin-dependent protein kinase activity; calmodulin binding; identical protein binding; protein binding; protein homodimerization activity; protein serine/threonine kinase activity; sodium channel inhibitor activity; titin binding; transmembrane transporter binding; ATP binding; protein kinase activity; protein serine kinase activity
Biological process: negative regulation of sodium ion transmembrane transport; positive regulation of cardiac muscle hypertrophy; protein phosphorylation; regulation of cellular localization; regulation of membrane depolarization; regulation of relaxation of cardiac muscle; cardiac muscle cell contraction; cellular response to calcium ion; endoplasmic reticulum calcium ion homeostasis; long-term synaptic potentiation; positive regulation of cardiac muscle cell apoptotic process; regulation of calcium ion transmembrane transport via high voltage-gated calcium channel; regulation of cardiac muscle cell action potential; regulation of cardiac muscle cell action potential involved in regulation of contraction; regulation of cardiac muscle contraction by regulation of the release of sequestered calcium ion; regulation of cell communication by electrical coupling; regulation of cell communication by electrical coupling involved in cardiac conduction; regulation of cell growth; regulation of heart contraction; regulation of heart rate by cardiac conduction; regulation of neuronal synaptic plasticity; regulation of protein localization to plasma membrane; regulation of release of sequestered calcium ion into cytosol by sarcoplasmic reticulum; regulation of ryanodine-sensitive calcium-release channel activity; regulation of the force of heart contraction; and 2 more
Cellular component: calcium- and calmodulin-dependent protein kinase complex; membrane; cytoplasm; cytosol; endocytic vesicle membrane; endoplasmic reticulum membrane; neuron projection; nucleoplasm; nucleus; postsynaptic density; sarcolemma; sarcoplasmic reticulum membrane
Genetic constraint (gnomAD): Loss-of-function variants: 1 observed, 10.62 expected, observed/expected ratio (o/e) 0.0941, 90% interval 0.032 to 0.45. The upper end of that interval is the gene's LOEUF score, 0.45, which puts it in group 1 of 6, group 1 being the genes least tolerant of losing a copy. Missense variants: 99 observed, 136.58 expected, observed/expected ratio (o/e) 0.72, 90% interval 0.62 to 0.86. Synonymous variants: 43 observed, 46.48 expected, observed/expected ratio (o/e) 0.93, 90% interval 0.72 to 1.19.
Gene-disease validity (ClinGen):
ClinGen rates the evidence that CAMK2D causes each of these diseases.
CAMK2D-related neurodevelopmental disorder and dilated cardiomyopathy (autosomal dominant): Strong. A neurodevelopmental disorder caused by variation in the CAMK2D gene.
Homologues: Orthologues: dog CAMK2D (99% identical), pig CAMK2D (99% identical), rabbit CAMK2D (94% identical), zebrafish camk2d1 (83% identical). Paralogues in human: CAMK2B (84% identical), CAMK2G (82% identical), CAMK2A (79% identical), CAMK1D (27% identical), CAMK1G (27% identical), CAMK1 (27% identical), DCLK1 (25% identical), DCLK2 (25% identical), PNCK (25% identical), PHKG2 (25% identical), PHKG1 (25% identical), PSKH1 (23% identical), and 10 more.
Diseases named in the same sentence as CAMK2D in open-access papers:
CAMK2D is named in the same sentence as 61 diseases in open-access papers, as found by Europe PMC text mining. Sharing a sentence is not in itself a finding about the gene and the disease. The quoted sentences say what the papers report.
heart failure (11 papers, 2013 to 2026). Inability of the heart to pump blood at an adequate rate to meet tissue metabolic requirements. "The increased autoAb expression against CAMK2D is intriguing, as this protein is implicated in cardiac hypertrophy and heart failure, conditions which have also been reported to coexist with MMD." (PMID 23518061, 2013). "However, heart failure has been associated with increased CaMK2D expression, implicated in decreased cardiac contractile properties, uncoupled cardiac excitation-contraction and possible sudden death." (PMID 26840416, 2016). "Camk2d is predominantly found in cardiac tissue, and its expression alters during cardiomyocyte differentiation, heart failure, and ischemia." (PMID 33240041, 2020). "Likewise, BBLN as a CAMK2D enhancer, triggered the immune system pathway, with prominent upregulation of heart failure-enhancing transcripts in Tg-BBLN mice and TOF patient heart specimens with cyanosis." (PMID 38666071, 2023). "In our study, we found a strong upregulation of calcium/calmodulin dependent protein kinase II delta (CAMK2D), a protein that has been related to the onset of heart failure in addition to its well‐known functions in calcium signaling transduction, cytoskeleton organization, and protein secretion." (PMID 37565451, 2023). "Downregulation of CAMK2D by an interfering RNA retarded BBLN-induced symptoms of heart failure." (PMID 38666071, 2023). "In heart failure and cardiomyopathy, RBPMS cooperates with RBM20 to regulate splicing of sarcomeric genes such as TTN, safeguarding contractile integrity, while DDX5 maintains calcium homeostasis through CAMK2D splicing, and loss of QKI results in profound sarcomere disarray and heart failure." (PMID 41399527, 2025). "Colocalisation with heart failure implicates 23 shared loci and bioinformatic analysis prioritises genes including HSPB7, CAMK2D, ALDH2, ENG, and YWHAE." (PMID 41760662, 2026). "Findings from GWAS and Mendelian randomization-proteomics identify seven (CAMK2D, PRKD1, PRKD3, MAPK3, TNFSF12, APOC3 and NAE1) proteins as potential targets for interventions to be used in primary prevention of heart failure." (PMID 37429843, 2023). "The reported findings overall suggest that reduced Camk2d signaling cascades, and not exclusively upregulation, may contribute to electrical instability and heart failure." (PMID 35306519, 2022).
cardiac hypertrophy (10 papers, 2013 to 2025). "An increased expression of Camk2d has previously been associated with ventricular hypertrophy in humans and cardiomyopathy in mice." (PMID 38533084, 2024). "Similar to CAMK2D, abnormal activation of the cardiac renin-angiotensin system is associated with cardiac hypertrophy." (PMID 32228691, 2020). "Likewise, the phosphorylation of the Ser333 and Thr366 residues of CAMK2D have been implicated in increased cardiac hypertrophy and inflammation." (PMID 40753091, 2025). "Camk2d (Ca2+/calmodulin-dependent protein kinase II) is known to play an important role during cardiac hypertrophy." (PMID 40440080, 2025). "Both Camk2d and Hdac1 are previously reported to regulate cardiac hypertrophy." (PMID 38533084, 2024). "It was consequently suggested that target-specific inhibition of Camk2d may be a useful treatment of cardiac hypertrophy." (PMID 25368602, 2014). "The role of this protein in cardiac pathology was more clearly established in a knockout mouse model where animals exhibited normal heart function but when stress was applied in the form of pressure overload, cardiac hypertrophy did not develop in the absence of CAMK2D." (PMID 32228691, 2020).
cardiomyopathy (5 papers, 2017 to 2026). A disease of the heart muscle or myocardium proper. "These include known Mendelian cardiomyopathy risk genes such as FLNC and ACTN2, and novel regulatory candidates like CAMK2D, LMF1, MYOZ1, SKI, SYNPO2L, and TKT." (PMID 41646816, 2026). "While most research on RBM20 splicing targets has focused on titin (TTN), multiple studies over the last years have shown that other splicing targets of RBM20 including Ca2+/calmodulin-dependent kinase IIδ (CAMK2D) might be critically involved in the development of RBM20 cardiomyopathy." (PMID 32789749, 2020).
ovarian carcinoma (5 papers, 2022 to 2025). A malignant neoplasm originating from the surface ovarian epithelium. "In a study conducted with ovarian cancer, it was shown that high expression of the CAMK2D gene conferred resistance to cells in Cisplatin treatment." (PMID 40579643, 2025). "Together, inhibition of the Ca2+ mediated CAMK2D/CREB1 pathway appears to be a promising therapeutic target for doxorubicin resensitization in ABCB1-mediated MDR ovarian cancer." (PMID 36439493, 2022). "In this study, we reported that the CAMK2/CREB pathway, particularly CAMK2D, is a promising target for reversing ABCB1-mediated drug resistance in ovarian cancer." (PMID 36439493, 2022).
glioma (4 papers, 2017 to 2023). A benign or malignant brain and spinal cord tumor that arises from glial cells (astrocytes, oligodendrocytes, ependymal cells). "This association was in line with our finding that CAMK2D expression was associated with the decreased DSS in glioma patients." (PMID 32565801, 2020). "Calcium/calmodulin-dependent protein kinase type II subunit delta (Camk2d) plays a critical role in the invasion and metastasis properties of glioma cells and is down-secreted by macrophages after treatment with PCs inhibitor." (PMID 33402730, 2022). "In GBM-glioma subtype the order of expression from highest to lowest was as follows: CaMK2G > CaMK2B ≥ CaMK2A > CaMK2D." (PMID 28663722, 2017). "CAMK2D, EIF3K, MPC2, MYL12B, PAM, and SLC35B4, selected from the schizophrenia dataset and TCGA, were reevaluated in CGGA through gene expression in glioma grading and survival curves between patients having high level of gene expression and those having low level of gene expression." (PMID 32565801, 2020).
breast carcinoma (3 papers, 2016 to 2025). "In the breast cancer tissues, the most robust correlations have been detected between lnc_ZFP161/ lnc_FOXF1, CAMK2D/ lnc_ZFP161 and CAMK2D / lnc_FOXF1 (r = 0.86, 0.71 and 0.64 respectively)." (PMID 33742056, 2021). "In breast cancer tissues, the most robust correlations have been detected between lnc_ZFP161/lnc_FOXF1, CAMK2D/lnc_ZFP161 and CAMK2D/lnc_FOXF1." (PMID 33742056, 2021). "In breast cancer tissues, the most robust correlations have been detected between lnc_ZFP161/ lnc_FOXF1, CAMK2D/ lnc_ZFP161 and CAMK2D / lnc_FOXF1 (r = 0.86, 0.71 and 0.64 respectively)." (PMID 33742056, 2021). "We next assessed whether CaMKII expression is associated with breast cancer patient outcome by examining CAMK2A, CAMK2B, CAMK2G and CAMK2D mRNA expression in a publically available 1881-sample breast cancer data set25." (PMID 27605043, 2016). "Of note, this analysis emphasised the importance of high expression of both PEAK1 and CAMK2D, consistent with a co-activating PEAK1/CAMK2D ‘cassette’ promoting breast cancer progression." (PMID 39984440, 2025). "We identified down-regulation of OXTR, FOS, ITPR1, RCAN1, CAMK2D, CACNA2D and lnc_ZFP161, and up-regulation of lnc_MTX2 in the breast cancer tissues compared with nearby non-cancerous tissues." (PMID 33742056, 2021). "Expression levels of OXTR, FOS, ITPR1, RCAN1, CAMK2D, CACNA2D and lnc_ZFP161 were significantly down-regulated in the breast cancer tissues compared with nearby non-cancerous tissues." (PMID 33742056, 2021). "Expression levels of OXTR, FOS, ITPR1, RCAN1, CAMK2D, CACNA2D and lnc_ZFP161 were significantly down-regulated in breast cancer tissues compared with nearby non-cancerous tissues." (PMID 33742056, 2021).
dilated cardiomyopathy (3 papers, 2023 to 2025). Cardiomyopathy which is characterized by dilation and contractile dysfunction of the left and right ventricles. "For instance, Rbm20 knockout mice exhibit dilated cardiomyopathy (DCM) due to the disrupted splicing of genes such as Titin and Camk2d, impairing sarcomere structure and calcium signaling." (PMID 40076920, 2025).
gastric cancer (3 papers, 2020 to 2022). A primary or metastatic malignant neoplasm involving the stomach. "However, the biological function and the epigenetic regulation of CAMK2D in gastric cancer are not fully understood." (PMID 34131397, 2021).
ischemia (3 papers, 2016 to 2020). A hypoperfusion of the BLOOD through an organ or tissue caused by a PATHOLOGIC CONSTRICTION or obstruction of its BLOOD VESSELS, or an absence of BLOOD CIRCULATION. "In this study, we report the discovery of C2dat1, the first CAMK2D-associated lncRNA, induced by I/R in murine focal cerebral ischemic models, which may be neuroprotective during ischemia-induced neuronal injury." (PMID 27031970, 2016). "In summary, focal ischemia induced a parallel increase in C2dat1 and CAMK2D mRNA in mouse model of I/R with differential patterns in ischemic core and penumbra regions." (PMID 27031970, 2016). "Our data indicated that CAMK2D/CaMKIIδ and CAMK2G/CaMKIIγ were selectively upregulated in a time-dependent manner at both transcriptional and protein levels after acute ischemia." (PMID 29992531, 2019).
Alzheimer disease (2 papers, 2024 to 2025). A progressive, neurodegenerative disease characterized by loss of function and death of nerve cells in several areas of the brain leading to loss of cognitive function such as memory and language. "From the comparison of FOS exclusively defined by two questionnaires, interaction signals around peroxisomal biogenesis factor 26 (PEX26), EED, and CAMK2D were replicated in all-cause dementia, Alzheimer's disease, and vascular dementia outcomes, respectively." (PMID 40949174, 2025).
Arrhythmia (2 papers, 2023 to 2024). Any cardiac rhythm other than the normal sinus rhythm. "We propose that altered calcium activity due to disruption of grin2bbART, a putative lncRNA in bigheart, altered the Camk2d-Hdac pathway, causing heart arrhythmia and hypertrophy in zebrafish." (PMID 38533084, 2024). "CAMK2D, and CACNA1E, that are associated with abnormal calcium handling and arrhythmias respectively, were increased in multiple types of cardiac cells (e.g., CM, neuron, and fibroblast)." (PMID 37084237, 2023). "Arrhythmia and the cardiac chamber enlargement in bigheart may be a result of altered calcium handling, possibly via the Camk2d-Hdac1 pathway." (PMID 38533084, 2024).
glioblastoma (2 papers, 2018 to 2021). The most malignant astrocytic tumor (WHO grade IV). "Also,ZC3H18,SLIT2 CARF,GPATCH4,CAMK2D,BCORL1,ARHGAP4mutations were found in glioblastoma (T03)." (PMID 34430964, 2021).
lung carcinoma (2 papers, 2020 to 2021). "CAMK2D is a novel tumor suppressor, which has been found to be inactivated in several types of cancers, including colorectal cancer, prostate cancer, and lung cancer 35-37." (PMID 34131397, 2021). "To study whether CAMK2D might play a TIC supporting role in lung cancer, we knocked down CAMK2D by siRNA in HCC827 cells, and the effect on TIC phenotypes was studied." (PMID 32483123, 2020).
neuroblastoma (2 papers, 2016 to 2022). Neuroblastoma (NB) is the most common solid, extracranial childhood tumor. "Using mouse neuroblastoma (N2a) cells, we further evaluated the expression of C2dat1 and CAMK2D/CaMKIIδ in response to in vitro ischemia." (PMID 27031970, 2016).
Obesity (2 papers, 2016 to 2019). Accumulation of substantial excess body fat. "Until now, the specific roles of ANO2, CAMK2D, SLC8A1, PDE2A, CALML3, GNG7, and CALML6 genes in olfactory-related dietary patterns and obesity in humans have not been apparently explored; therefore, further investigation in these research areas is warranted." (PMID 31057674, 2019).
cocaine addiction (1 paper, 2020).
colorectal cancer (1 paper, 2021). A primary or metastatic malignant neoplasm that affects the colon or rectum. "CAMK2D was frequently decreased in colorectal cancer and was associated with poor prognosis." (PMID 34131397, 2021).